SSTR2 (somatostatin receptor 2)
Diseases named in the same sentence as SSTR2 in open-access papers (continued):
Sharing a sentence is not in itself a finding about the gene and the disease.
tumor (continued). "In vivo evaluation in mice bearing xenografted AR42J or HCT116 (SSTR2-) tumors showed a tumor uptake of 7.20 ± 0.74% ID/g at 1 h p.i., which was superior to [[68Ga]Ga-DOTA-TATE] showing an accumulation of 5.75 ± 0.55% ID/g." (PMID 40430268, 2025). "This PDC exhibited remarkable selectivity and anti-tumor efficacy in SSTR2-overexpressing cell lines, including IMR32, CFPAC-1, MOLT-4, and PC-3." (PMID 40428099, 2025). "Anti-tumoral bystander mechanisms also suppressed tumor angiogenesis in peripheral tumor vessels; in vivo SSTR2 transfer into human PDAC tumors markedly reduced microvessel density and VEGF expression, while Sstr3 was upregulated." (PMID 40134804, 2025). "Both in vitro and in vivo experiments corroborated the efficacy of the anti-SSTR2 ADC in tumor growth inhibition." (PMID 40170861, 2025). "Sstr2 was injected into either exponentially growing pancreatic primary tumors or hepatic metastases followed by investigation of transgene expression and tumor progression 5-6 days post-injection." (PMID 40134804, 2025). "This conjugate showed specific binding to SSTR2 and greater efficacy in reducing tumor growth in MCF-7 breast cancer cell lines." (PMID 40428099, 2025). "In preliminary studies, these radiolabeled antagonists show a higher tumor uptake due to higher affinity binding to SSTR2 as compared to the agonists." (PMID 40064181, 2025). "Since antagonists can bind to more tumor targets than agonists, a paradigm shift in binding from internalizing SSTR2 agonists to antagonists is feasible." (PMID 40943459, 2025). "The MDT recommended repeating [68Ga]Ga-DOTATATE imaging to reassess tumor burden and SSTR2 expression." (PMID 41210247, 2025). "Consistently, in this study, [212Pb]Pb-DOTAM-JR11 has shown favorable tumor retention compared with other SSTR2-targeting analogs." (PMID 39884771, 2025). "The strong expression of SSTR2, in particular, enhances the sensitivity of tumor cells to SSA-induced apoptotic signaling." (PMID 39996718, 2025). "SSTR antagonists have been shown to lead to higher tumour dose and tumour‐to‐organ ratios than agonists in pre‐clinical research, due to their capability to bind to the SSTR2 in its active and inactive states." (PMID 39563515, 2025). "Expression of cloned Sstr2 induced both anti-oncogenic and local anti-tumor bystander effects in vivo (see also section 5.3)." (PMID 40134804, 2025). "In routine diagnostics, the responsible pathologist often needs to prioritize immunohistochemical stains essential for determining neuroendocrine differentiation, tumor grade, and primary site of origin before SSTR2 staining can be considered." (PMID 41450443, 2025). "In vivo SSTR2 transfer into human PDAC tumors strongly inhibited tumor growth and progression by inducing intra-tumoral production of SST." (PMID 40134804, 2025). "The conjugates, linked via a disulfide-bridged cyclic conformation of 3207-86, demonstrated exceptional biological stability and enhanced anti-tumor efficacy in SSTR2-overexpressing HCT116, H1299, and TRAMP C2 cell lines." (PMID 40428099, 2025). "We also showed that 68Ga-DOTATATE PET/CT imaging can effectively localize HCC in subcutaneous tumor models with varying SSTR2 expression levels and an HCC patient with spinal metastases." (PMID 39857944, 2025). "The similar binding patterns on both tumor cells and bone marrow stem cells suggest an SSTR2-mediated binding mechanism in both cases." (PMID 40521188, 2025). "For instance, in a comparative preclinical study, the SSTR2 antagonist 177Lu-OPS201 showed superior tumor uptake and longer tumor retention in SSTR2-expressing xenografts compared with the agonist [177Lu]Lu-DOTATATE." (PMID 39884771, 2025). "Subsequently, we wanted to understand if ligand binding is higher or lower than on SSTR2-expressing tumor cells." (PMID 40521188, 2025).
tumor (continued). "The fluorescent SSTR2 antagonists also showed several-fold higher receptor-specific binding than agonists to tumor cells, as it was the case for the clinically used SSTR2 radioligands." (PMID 40521188, 2025). "We also discovered a superior tumor-to-kidney area under the curve ratio for [212Pb]Pb-DOTAMTATE over other SSTR2-targeting peptides when radiolabeled with 212Pb." (PMID 39884771, 2025). "We further explored the relationship between clinicopathological factors (age, sex, tumour size) and the extent and intensity of SSTR2 expression." (PMID 40770587, 2025). "Increased SSTR2 has been reported upon radiation in other cancers, making SSTRs good targets for theranostics of various NE tumours and potentially applicable to NE‐enriched PCa." (PMID 39840448, 2025). "Somatostatin analogs (SSAs), such as octreotide and lanreotide, bind to SSTR2 to control hormone-related symptoms and inhibit tumor growth." (PMID 41210247, 2025). "In vivo studies demonstrate that PEN-221 precisely targets tumours overexpressing SSTR2, inducing profound and sustained tumour regression across multiple xenograft mouse models." (PMID 41463450, 2025). "For example, the results suggest increased SSTR2 expression in this tumor subtype, as previously reported, but this observation is notably biased by its very high expression in one out of three samples." (PMID 40813692, 2025). "Namely, various studies based on immunohistochemistry demonstrated the expression of all SSTR1 to SSTR5 on primary NB and, specifically, the overexpression of SSTR2 in the majority of NBs, even in recurrent/refractory tumor disease." (PMID 40064181, 2025). "The development of peptide receptor radionuclide therapy (PRRT) has introduced a promising therapeutic strategy by leveraging SSTR2 expression to enable highly sensitive imaging of small tumors and the delivery of targeted radiation directly to tumor cells." (PMID 40389624, 2025). "Impressive preclinical responses suggest that TAT has a high potential for anti‐tumor efficacy in SSTR2‐overexpressing cancers." (PMID 40064181, 2025). "Systemic therapy for pNETs has traditionally focused on somatostatin analogs (SSA) due to the high expression of somatostatin receptor type 2 (SSTR2) on tumor cells." (PMID 40389624, 2025). "Studies show a strong correlation between SUVmax, tumor size, and somatostatin receptor 2 (SSTR2) expression." (PMID 40364111, 2025). "The overproduction of GCs, characterizing patients with CD, results in the upregulation of miR-375 and consequent downregulation of SSTR2 expression levels in corticotroph tumor tissue." (PMID 40488558, 2025). "The lowest MFI were observed in CD34+/CD38+ cells and in H69 cells, which are a SSTR2-low expressing tumor model." (PMID 40521188, 2025). "Our novel observations suggest a potential link between SSTR2 expression, receptor tyrosine kinase expression, tumor metastasis, clinical outcomes, and therapeutic sensitivity." (PMID 41002582, 2025). "Using the TNMplot web-based analytical tool, we evaluated the mRNA expression levels of SSTR2 across 22 different human cancer types by comparing matched tumor and adjacent normal tissue samples." (PMID 41002582, 2025). "Immunohistochemical analysis revealed weak positivity for epithelial membrane antigen (EMA) in some tumor cells, with diffuse expression of somatostatin receptor 2 (SSTR2) and vimentin." (PMID 41013491, 2025). "We calculated all SSTR2 analogs’ AUC for kidneys and tumors including tumor-to-kidney ratios (T/K AUC ratio)." (PMID 39884771, 2025). "Specifically, after orthotopic implantation of PC-1.0 cells into Syrian golden hamsters both tumor growth and metastatic progression of allografts containing 100% of SSTR2 expressing cells were inhibited for up to 20 days after implantation." (PMID 40134804, 2025).
tumor (continued). "Peptide receptor radionuclide therapy combines somatostatin analogs with a therapeutic radionuclide, such as 177Lu, 90Y, or 212Pb, which emits radiation to selectively target and destroy SSTR2-expressing tumor cells." (PMID 39884771, 2025). "This therapeutic radiopharmaceutical had shown promising preclinical data with significantly higher tumor uptake and improved tumor-to-normal organ ratio compared to the clinically used SSTR2 agonists like 177Lu-DOTA-TATE (Lutathera) 21-24." (PMID 40521188, 2025). "It was discovered that [212Pb]Pb-DOTAMTATE has a superior T/K AUC ratio over other SSTR2-targeting peptides when radiolabeled with 212Pb, indicating favorable tumor retention and a more favorable dosimetry profile." (PMID 39884771, 2025). "In rectal NETs, approximately two-thirds of patients exhibit SSTR2 expression, which correlates with smaller tumor size, lower tumor stage, and improved overall survival." (PMID 41002582, 2025). "All three tumor types commonly feature the overexpression of somatostatin subtype receptors 2 (SSTR2), which can be visualized with [68Ga]Ga-DOTA-SSTR PET radiotracers." (PMID 38791956, 2024). "Lutathera preferentially binds to SSTR2, which is overexpressed in tumor cells and subsequently undergoes internalization." (PMID 38473389, 2024). "Here, we have confirmed—for the first time—in human PDAC-derived tumor cells a strong positive regulation of SSTR2 by TGF-β1." (PMID 39682758, 2024). "Conclusion:68Ga-FAPI-LM3 exhibited FAPI and SSTR2 dual-receptor–targeting properties both in vitro and in vivo, resulting in improved tumor uptake and retention compared with that observed with monomeric 68Ga-FAPI and 68Ga-DOTA-LM3." (PMID 38176714, 2024). "The observed fluorescence signal was largely correlated with SSTR2 IHC staining and accurately represented pNET tumor extension, which suggests strong utility for fluorescence-guided surgical applications." (PMID 38267640, 2024). "Impressive preclinical responses indicate that TAT has a high potential for anti-tumour efficacy in SSTR2-overexpressing cancers." (PMID 38543120, 2024). "Fluorescence imaging showed excellent co-localization of MMC(FNIR-Tag)-TOC with SSTR2-positive areas and small multifocal lesions (approximate size: 600–900 μm) that were within the tumor boundary, as confirmed by H&E and IHC staining." (PMID 38267640, 2024). "To assess PRRT efficacy, we demonstrated specific uptake of 177Lu-DOTA-TATE via somatostatin receptor subtype 2 (SSTR2), which was highly overexpressed in the majority of tumor samples." (PMID 39061156, 2024). "An immunohistochemical analysis demonstrated heterogeneity of SSTR2 expression in the tumor lesions." (PMID 39324010, 2024). "Quantification of the SSTR3, SSTR2, and SSTR5 transcript levels in tumor tissues revealed a similar expression of SSTR3 compared to SSTR2 and SSTR5 in our cohort of patients." (PMID 38612419, 2024). "For control purposes, the in vivo performance of [68Ga]Ga-TATE-46 was investigated in MC38 tumor-bearing mice, which exhibit low expression of SSTR2 and FAP." (PMID 39770488, 2024). "By characterizing the absorbed radiation dose in separate tumor lesions and corresponding SSTR2 expression patterns, the trial strives to understand the factors that contribute to 177Lu-DOTATATE treatment response and resistance." (PMID 39324010, 2024). "The study also confirms that modifying the radiometal can alter the biodistribution and tumor uptake of the radiopetides towards SSTR2." (PMID 39149492, 2024). "Here, we report a case in which preoperative examination indicated a potential tumor with low somatostatin receptor 2 (SSTR2) and SSTR5 expression, whereas postoperative pathological examination indicated strong SSTR expression." (PMID 39507000, 2024). "This study demonstrated the feasibility and efficacy of 68Ga-FAPI-LM3, a divalent molecule for PET imaging of FAP and SSTR2, emphasizing its clinical utility for tumor detection and staging in patients with NPC." (PMID 38176714, 2024).
tumor (continued). "We performed a qualitative analysis and evaluated the correlation between the fluorescence staining pattern and SSTR2 distribution in the tumor and surrounding normal areas of the sections." (PMID 38267640, 2024). "Herein, we report a case where preoperative examination indicated a suspected tumor with low SSTR2 and SSTR5 expression, whereas postoperative pathological examination revealed strong SSTR expression." (PMID 39507000, 2024). "SSTR2 is the most widely expressed receptor in human tumours and has the strongest antitumor properties." (PMID 39011594, 2024). "The current study investigates the potential of harnessing tumor infiltrating CAR T cells expressing SSTR2 to capture 177Lu-DOTATATE for TRT." (PMID 38550578, 2024). "Metastatic tumor lesions consistently exhibited weak SSTR2 staining and predominantly undifferentiated NB cell morphology." (PMID 39324010, 2024). "Well-differentiated tumors are also candidates for PRRT and somatostatin analogue therapy, which targets SSTR2-expressing tumor cells." (PMID 39649120, 2024). "Consistent with prior research, we reaffirm the strong roles of SSTR2 expression and DG tumor patterns in predicting favorable outcomes to fgSRL." (PMID 39201352, 2024). "SSTR2 IHC signal was positive in tumor regions, with strong and widespread staining intensity in all cases except one, where variable intensity was seen as indicated by areas of both strong (solid line) and weak (dashed line) staining in the tumor." (PMID 38267640, 2024). "By contrast, the new SSA analog named pasireotide demonstrated a strong antiproliferative effect in these tumor cells, characterized by a high expression of SSTR2 and SSTR5." (PMID 39064468, 2024). "The delivery vehicle we developed is an octreotide-DSPE-PEG-liposomal formulation loaded with paclitaxel, engineered to maximize drug delivery efficiency to tumor cells overexpressing SSTR2." (PMID 38791582, 2024). "First, the preclinical tumor model involved transfected cell lines with extremely high FAP/SSTR2 expression." (PMID 38176714, 2024). "In 43 patients with available surplus tumor tissue samples, hottest lesion SUVmax/TLRpeak showed a significant correlation with the level of SSTR2-expression by tumor cells in IHC (Spearman's rho 0.86/0.81, both p < 0.001; ANOVA p < 0.001)." (PMID 39310095, 2024). "Statistical significance was reached for SSTR2 score in IHC as well as for SUVmax and TLRpeak of the hottest lesion per patient and whole-body tumor TLRmean in 68Ga-SSO120 PET." (PMID 39310095, 2024). "The primary tumor sample collected 19 months later (4 months after 177Lu-DOTATATE treatment) displayed a heterogeneous SSTR2 expression." (PMID 39324010, 2024). "They act by reducing GH production and induce tumor size shrinkage by binding to somatostatin receptors (SSTRs) on the pituitary tumor, with SSTR2 and the SSTR5 being the most prevalent and studied receptor types." (PMID 39201352, 2024). "The treatment-naïve primary tumor sampled at diagnosis displayed cytoplasmic SSTR2 staining in more than 50% of NB cells." (PMID 39324010, 2024). "QUESTION: Does a heterobivalent molecule that recognizes both FAP and SSTR2 demonstrate improved efficacy in tumor-targeting and in vivo pharmacokinetics compared with those of its corresponding monomers?" (PMID 38176714, 2024). "In contrast to SSTR2, IGF-1R has been implicated in tumor growth, invasion, and metastasis, and the binding of IGF-1 and IGF-1R triggers a proliferative and anti-apoptotic signaling cascade." (PMID 39238765, 2024). "We analyzed the SSTR2 expression patterns in tumor biopsies collected throughout the course of the disease and correlated SSTR2 expression with absorbed radiation doses and treatment response in the separate tumor lesions." (PMID 39324010, 2024). "These tracers exhibit a strong affinity for SSTR2 while binding to other relevant subtypes in certain tumour types." (PMID 39258048, 2024).
tumor (continued). "During PRRT, SSTR2 on the tumor cell surface is targeted by the somatostatin analog DOTA-TATE, after which the coupled radionuclide lutetium-177 locally induces DNA damage after radioactive decay." (PMID 39061156, 2024). "Functional imaging refers to somatostatin receptor scintigraphy (SRS), a technique that targets somatostatin receptor 2 (SSTR2), which is primarily expressed in tumor cell membranes." (PMID 39749027, 2024). "SSTR2 expression in IHC was evaluated on a 4-level scale and correlated with normalized standardized uptake values and tumor-to-liver ratios (SUVmax and TLRpeak) in 68Ga-SSO120 PET on a lesion level." (PMID 39310095, 2024). "In SSTR2-positive xenograft-bearing mice, the combination of nedisertib (a DNA-PK specific inhibitor) and LuTate produced a more robust control of tumour growth and increased survival compared to LuTate alone." (PMID 37771787, 2023). "By Reubi and Waser, most GLP-1R-positive tumours showed SSTR2, while the expression of SSTR1, 3, 4 and 5 was lower." (PMID 37894845, 2023). "Somatostatin receptors, specifically somatostatin receptor subtype 2 (SSTR2), are overexpressed in paediatric tumours." (PMID 36673002, 2023). "In an in vivo PNET xenograft model with low basal SSTR2 expression, our studies demonstrate significantly higher tumor uptake of SSTR2-targeted 177Lu-DOTATATE in animals pretreated with HDACis compared with controls." (PMID 37487000, 2023). "Clinical data were extracted from medical records, and immunohistochemistry (IHC) for SDHB and SSTR2 was performed in patients with available tumor tissue." (PMID 36946182, 2023). "The aim of this therapy is to target receptors overexpressed on tumours (e.g. SSTR2), leading to the irradiation of tumour cells and the surrounding blood vessels and inhibiting angiogenetic response." (PMID 37434648, 2023). "In contrast, SSTR2 induced cytotoxic and cytostatic effects and inhibited tumour cell proliferation." (PMID 38203605, 2023). "Moreover, it is unclear whether there is an association between SSTR2 imaging and an effective response to SSAs, as it is possible that the presence of even a few receptors may in fact lead to a response to SSAs that affects the whole tumour burden." (PMID 36980746, 2023). "Here, we aimed to restore SSTR2 expression through the reversal of inhibitory epigenetic gene silencing to improve tumor responsiveness to PRRT." (PMID 37487000, 2023). "Treatment of NETs by targeting SSTR2 signaling pathway was previously demonstrated to induce hormone secretion and tumor apoptosis." (PMID 36810324, 2023). "It should be noted that 90Y-DOTATOC takes advantage of a higher β particle emission as compared to 177Lu-DOTATATE; however, 177Lu-DOTATATE shows higher SSTR2 affinity, a longer residence time in tumor and a lower kidney exposure." (PMID 37444593, 2023). "We also aimed to evaluate the correlation of the functional predictive results of the sAOT with the expression of those molecular tumor biomarkers with high predictive capacity, such as E-cadherin and SSTR2." (PMID 38027102, 2023). "SSTR2-mediated regulation of tumour growth is further supported by the receptor-induced activation of caspase-8 and post-transcriptional downregulation of antiapoptotic protein Bcl-2, as well as the upregulation of TNFα and TRAIL receptors." (PMID 38203605, 2023). "The use of SSTR2-induced cytotoxic effect and Notch signalling regulator valproic acid has been proposed in combination as a potential therapeutic intervention in SCLC by suppressing tumour growth and increasing SSTR2 expression." (PMID 38203605, 2023). "Noteworthy, various studies have shown that antagonists have favourable pharmacokinetic profiles and better tumour visualization compared to agonists, thanks to their ability to bind multiple conformational states of SSTR2, despite poor internalization rates." (PMID 36959237, 2023).